MINDY4B (MINDY family member 4B)
Synonyms: C3orf76; FAM188B2
Tractability: No criterion of Open Targets' tractability assessment is met for any kind of drug.
Gene: Protein-coding gene on chromosome 3 (150,870,376 to 150,905,439, reverse strand). Ensembl gene ENSG00000214237.
Gene Ontology:
Molecular function: K48-linked deubiquitinase activity; cysteine-type deubiquitinase activity
Biological process: protein K48-linked deubiquitination
Homologues: Orthologues: chimpanzee MINDY4B (99% identical), macaque MINDY4B (95% identical), pig MINDY4B (82% identical), dog MINDY4B (81% identical), rabbit MINDY4B (76% identical), mouse Mindy4b-ps (71% identical), rat Mindy4b (71% identical), tropical clawed frog MINDY4B (48% identical), zebrafish mindy4b (46% identical). Paralogues in human: MINDY4 (33% identical), MINDY3 (20% identical).
Diseases named in the same sentence as MINDY4B in open-access papers:
MINDY4B is named in the same sentence as 2 diseases in open-access papers, as found by Europe PMC text mining. Sharing a sentence is not in itself a finding about the gene and the disease. The quoted sentences say what the papers report.
tumor (1 paper, 2022). "MeRIP-qPCR results showed that the relative level of m6A modification in HDAC9, MINDY4B was significantly increased in ALV-J induced tumor livers, while the relative level of m6A modification of SOX7 in ALV-J induced tumor livers was significantly decreased." (PMID 35529873, 2022). "RT-qPCR analysis revealed that the lncRNA levels of HDAC9, CMPK2, MINDY4B were up-regulated in the ALV-J induced tumor livers (positive group) compared to the normal livers in the negative group, whereas lncRNA levels of ATOH8 and LOC100859478 were down-regulated in the positive group." (PMID 35529873, 2022).
MINDY4B also shares sentences with these, for which no sentence is quoted: breast carcinoma (1 paper).